TLR4 (toll like receptor 4)
Diseases named in the same sentence as TLR4 in open-access papers (continued):
Sharing a sentence is not in itself a finding about the gene and the disease.
infection (continued). "Furthermore, TLR2, but not TLR4, has been shown to be essential for efficient internalization of Aspergillus fumigatus conidia, since infection of macrophages deficient in TLR2 rendered reduced conidial cell entry." (PMID 24312679, 2013). "Indeed, it was shown that L. (Viannia) panamensis infection results in up-regulation of TLR1, TLR2, TLR3, and TLR4 expression, inducing activation of infected macrophages, whereas infection with L. donovani suppresses the TLR2–NF-κB–mediated pro-inflammatory cytokine response." (PMID 24098824, 2013). "By contrast, for other Gram-negative pathogens with highly acylated lipid A including Salmonella enterica or Escherichia coli, infection susceptibility and the response after stimulation with LPS were indistinguishable between mice expressing human or mouse TLR4/MD-2." (PMID 23071439, 2012). "Consequently, further studies are needed to establish whether TLR4 might effectively be involved in P. falciparum recognition and host response in humans and whether TLR4 could contribute to the control of infection." (PMID 22691414, 2012). "Importantly however, these findings using TLR4-deficient or control mice did not address how the discordance in LPS recognition by human compared with mouse TLR4/MD-2 impacts host defense after infection in humans." (PMID 23071439, 2012). "In addition, we found abrogation – or almost complete suppression – of infection by pseudoviruses containing the BaL or BR envelope glycoproteins in MDMs stimulated through TLR3 or TLR4, with only partial reduction observed in cells stimulated through TLR2, TLR7 or TLR9." (PMID 23028330, 2012). "Interestingly, up-regulated TLR genes were mainly involved in the TLR4 pathway.The up-regulation of TLR4 during infection was further validated in experiments studying regulation of membrane expression of TLR4 and secretion of proinflammatory cytokines in infected RAW cells." (PMID 22642811, 2012). "Interestingly, we found SLPs to activate NFκB but not IRF3, downstream of TLR4 which correlated with the observation that TRIF−/− mice did not have increased susceptibility or severity of infection." (PMID 21738466, 2011). "Although there is evidence that TLR-2 may play a regulatory role during infection with L. braziliensis and downregulate DC IL-12 production, all other studies implicate TLRs and TLR-4 ligation and MyD88 signalling in particular in the generation of protection against infection." (PMID 21664694, 2011). "The induced TLR4 may initiate the host immune and defense responses against Der-p2 infection." (PMID 21909400, 2011). "Since the lining of the urinary tract is highly enrichedin TLR4 molecules, administering TLR4 specific ligands directly to the urinary tract could trigger TLR4 mediated innate immune responses thereby enhancing local reactivity and resistance to infection." (PMID 21151974, 2010). "This study aims to examine the response associated with genetic variations of TLR4, the receptor for bacterial LPS, and a central intracellular signal transducer (TIRAP/Mal) on cytokine release and for susceptibility and course of severe hospital acquired infections in distinct patient populations." (PMID 20525286, 2010). "The response to infection was strongly reduced also in Tlr4−/− mice confirming our previous findings that Tlr4 signaling is essential for the innate immune response to UTI and suggesting that that inhibition of TLR4 responses may be protective at the mucosal level." (PMID 20886104, 2010). "We predicted that inefficient TLR4 stimulation by B. parapertussis LPS may result in the low level of neutrophil accumulation in response to infection over the first few days and may allow this pathogen to grow rapidly during this time, even in animals given a passive transfer of immune serum." (PMID 19169359, 2009).
infection (continued). "Bordetella bronchiseptica and B. pertussis stimulate robust TLR4 responses that are required to control the infection, but a close relative, B. parapertussis, poorly stimulates this receptor, and TLR4 deficiency does not affect its course of infection." (PMID 19169359, 2009). "It is possible that mutations that effect the innate immune function of TLR4, and hence the ability to fight infection, may be under negative selective pressure and therefore not establish as a common variant in the population." (PMID 19277200, 2009). "Here we have shown that after infection of non-vaccinated Tlr4-deficient mice the number of bacteria, and lung IL-1α and IL-1β expression are higher than in similarly treated wild-type controls, while bronchial LN cell IFN-γ and IL-17 production and splenocyte TNF-α production are lower." (PMID 18498620, 2008). "Therefore TLR4 may bridge oxidized lipoproteins, infection, inflammation and low shear stress in the pathogenesis of the disease." (PMID 17534423, 2007). "In addition, TLR2 deficiency did not influence the expression of TLR4 on lung macrophages or blood monocytes or granulocytes throughout the infection." (PMID 17676990, 2007). "Conversely, in TLR2 or TLR4 deficient mice acute, but not chronic infection is controlled." (PMID 16285886, 2005). "Once produced, IL-37 attenuated TLR2, TLR4 and NOD1-mediated activation and TLR-mediated IL-8 responses to H. pylori infection." (PMID 41689434, 2026). "Combined Pg infection and HFD produced the most severe phenotype, with synergistically elevated cytokines, heightened TLR4/NF-κB activation, marked suppression of PPARγ and Nrf2 signaling, reduced eNOS expression, and diminished nitric oxide bioavailability." (PMID 41750623, 2026). "Silencing of SLAMF1 or TLR4 had minimal impact on HMPV-induced IFNB1 mRNA expression, except for a reduction observed in SLAMF1-silenced MDMs at 20 h post-infection." (PMID 41346628, 2025). "The results show that H37Ra infection upregulated TLR4 at early stage, but downregulated for longer infection period or at high MOI infection." (PMID 40502714, 2025). "To help resolve this valid scientific concern we did a study in which we compared infection with L. interrogans in mice expressing fully competent tlr4 (C57BL6, C3H-HeN) versus mice that are tlr4 hyporesponsive (C3H-HeJ)." (PMID 39975062, 2025). "In leukocytes, PLAUR positively correlated with RIG-I and MDA5 which changed to TLR3, TLR6, and TLR8 with infection; PLAU, on the other hand, lost its correlation with TLR4 and TLR5 with COVID19." (PMID 40825056, 2025). "While DENV-2 infection-induced up-regulation of TLR2 and TLR7 mRNA during the early stages of infection (1.5 and 3 h.p.i), the mRNA expression of TLR2, TLR3, TLR4, TLR7, and TLR8 reaches its maximum peak of expression at 24 h.p.i." (PMID 40934228, 2025). "Members of the PE/PPE protein family are known to interact with an array of surface receptors to benefit infection, notably TLR2 and TLR4 (15, 53, –, 56)." (PMID 40787981, 2025). "The expression of TLR4 and p-ERK proteins continued to be significantly up-regulated after LPS infection at these three stages compared to normal pregnancy." (PMID 40564264, 2025). "To help resolve this scientific concern we compared infection of mice expressing competent tlr4 (C3H/HeN, C57BL6) versus tlr4 hyporesponsive mice (C3H/HeJ) with Leptospira interrogans serovar Copenhageni strain Fiocruz L1-130 over a period of two weeks." (PMID 40445994, 2025). "In the case of studying exacerbated/lethal host responses that can occur in severe human infections and pathologies associated with specific immune mechanisms, future studies may need to employ mice lacking specific immune factors of interest rather than TLR4." (PMID 40817088, 2025). "During productive infection (characteristic of CIN1), an intact L1 protein facilitates virion assembly, triggering immune recognition through TLR4/NF-κB pathways." (PMID 40429372, 2025).
infection (continued). "Our results revealed a significant parabolic increase in TLR2, TLR4, TLR7, and TLR10 expression following infection, with TLR2—the primary receptor for S. aureus recognition—showing the most pronounced response." (PMID 41305370, 2025). "Toll-like receptor 4 (TLR4) is a crucial pattern recognition receptor (PRR) on innate immune cells, triggering the production of inflammatory cytokines in response to infection or tissue damage." (PMID 41153963, 2025). "Collectively, these results indicate that C. albicans infection initiates macrophage inflammatory responses through the TLR4/NF-κB/NLRP3 pathway, amplifying tissue inflammation via cascading effects and leading to severe infection." (PMID 41008953, 2025). "Specifically, the fimbriae trigger Toll-like receptor 4 (TLR4)-mediated activation, resulting in the production of proinflammatory cytokines and chemokines that recruit immune cells to the site of infection." (PMID 40573990, 2025). "TLR4 overexpression significantly increased HMPV-stimulated TNF and IFNB1 mRNA levels at later stages of infection." (PMID 41346628, 2025). "Gene expression of interleukin (IL)-6, IL-8, TLR2, TLR4, IL-1 alpha (IL-1α), and CXCR1 was evaluated by quantitative real-time polymerase chain reaction at 0, 6, 12, 24, 48, and 72 h post-infection." (PMID 40453956, 2025). "Specifically, alterations in the expression of these receptors in different regions have been observed during infection, decreasing the transcription of TLR-3, TLR-4, and TLR-9 when the disease progresses." (PMID 40725420, 2025). "Our results show that calf tracheal tissues revealed significantly elevated expression levels of TLR2, TLR4, TLR7, and TLR10, as well as MyD88 after infection with M. bovis, and initiated the innate immunity Toll-like receptor signaling pathway." (PMID 40005807, 2025). "infection, several TLRs have been identified, among which TLR-2, TLR-4, and TLR-9 stand out, which are involved in the detection of parasite-derived components and the subsequent activation of the immune response." (PMID 40725420, 2025). "Further observations also found that while both rKaSPI and rAdSPI promoted TLR-4 expression, T. spiralis infection also involves the regulation of TLR-1 and TLR-2 expression, highlighting the complexity of the parasite’s infection mechanism." (PMID 39799330, 2025). "Infection significantly disrupted eNOS coupling, depleted NO and BH4, elevated ROS, suppressed Nrf2 signaling, activated TLR4/NF-κB, impaired PI3K/AKT signaling, and triggered Fas–caspase-mediated apoptosis." (PMID 41294830, 2025). "However, since our study was performed using bone marrow neutrophils, we do not rule out the possibility that elicited neutrophils may induce CD14 expression during infection or are able to reprogramme themselves to undergo TLR4-driven cell death at the site of infection." (PMID 38965211, 2024). "Mechanistically, E. coli activates the TLR4 signaling in CD45+F4/80+Ly6G−Ly6C−CD11b+CD11c+ macrophages, resulting in aggravation of lung inflammation during infection." (PMID 39429884, 2024). "We found that TNF-α, IL-β, CXCL2, TLR4, and IL-6 (mRNA) and selected proteins (TNF-α, IL-1β, and CXCL2) were upregulated significantly by exposure to the particulate and infection." (PMID 38928968, 2024). "All of this is consistent with previous reports showing that lincRNA-Cox2 is overexpressed in a MyD88-dependent manner in response to the activation of various TLRs such as TLR2, TLR4, TLR7/8, or in response to infection with Listeria monocytogenes." (PMID 38464511, 2024). "Among 35 articles, some of the studies demonstrated the response of TLR4 and TLR5 along with the TLR2 response during the infection of Leptospira spp./cell components." (PMID 39729468, 2024). "During infection, TLR2 and TLR4, which are members of the TLR family, are widely recognized as the most important pattern recognition receptors because they can be activated by multiple antigens." (PMID 38716051, 2024).
infection (continued). "E. coli activates the TLR4 signaling in CD45+F4/80+Ly6G−Ly6C−CD11b+CD11c+ macrophages, resulting in aggravation of lung inflammation during infection." (PMID 39429884, 2024). "The impact of the impaired ability of the Mφ ΔTLR2/TLR4, Mφ ΔTRIF/TRAM, and ΔMyD88 to sense SH3b2 or EVs was evaluated in MNV-1 infection assays." (PMID 39712028, 2024). "The TIRAP 180 L allele has been shown to increase the innate immune response to TLR4 and TLR2 ligands and is related to increased resistance to infection." (PMID 38716051, 2024). "Here, we observed higher TLR2, TLR4, TLR5, TLR6, TLR8, TLR9, Myd88, NLRP3, ASC, and TNF-α mRNA expression at seven weeks after infection by S. mansoni in BALB/c and C57BL/6 mice compared to Swiss mice." (PMID 38896633, 2024). "While Mtb CDC1551 infection significantly upregulated the expression of IL8, expression of TLR4, PPARG, and STAT1 was significantly upregulated in Mtb HN878-infected trained and restimulated macrophages, compared to the cells without restimulation." (PMID 38980014, 2024). "However, neither TLR-2−/− nor TLR-4−/− mice were more susceptible to infection." (PMID 38535182, 2024). "Blocked TLR4/MD2 complex and the downstream signaling pathway activation, which increased the trafficking of neutrophils, macrophages, and monocytes to the infection site and reduced the generation of inflammatory cytokines caused by LPS." (PMID 39760081, 2024). "Six TLRs recognize the presence of SARS-CoV-2 (TLR2, TLR3, TLR4, TLR7, TLR8, and TLR9), of which TLR2, TLR4, and TLR9 favor the pathogenicity of the virus, while TLR3, TLR7, and TLR8 favor control of the infection and resolution of the disease." (PMID 39062904, 2024). "In undernutrition 65% + infection group, PD-1 (P = 0.0364), PD-L1 (P = 0.0481) and Bax (P = 0.0394) were conversely upregulated, and ICOS (P = 0.0274), TLR2 (P = 0.0097) and TLR4 (P = 0.0361) were also upregulated." (PMID 38185681, 2024). "Exposure to PM10 followed by infection significantly elevated relative mRNA levels for TNF-α, IL-1β, CXCL2, TLR4, IL-6, COX2, and iNOS when compared to control air (p < 0.001 for all)." (PMID 38928968, 2024). "It has been shown that SARS-CoV-2 spike protein binds TLR4 to increase the cell surface expression of ACE2 and facilitate viral entry exacerbating innate immune responses during infection." (PMID 37026002, 2023). "ASFV infection can activate the RLR and TLR signaling pathways, while TLR4 and TLR6 are significantly downregulated after infection." (PMID 37048502, 2023). "In this study, the expression levels of Tlr2 and Tlr4 were significantly upregulated after Pm HN01 and Pm HN02 infection, which was consistent with previous test results of P. multocida infection." (PMID 36838365, 2023). "Previous studies have indicated that the GBS hyaluronidase (HylB) can enhance systemic infection by breaking down host hyaluronan into disaccharides that dampen protective TLR2 and TLR4 signaling." (PMID 37747229, 2023). "Toll-like receptor 4 (TLR4), acting as a receptor for LPS, has a pivotal role in the regulation of immune responses to infection." (PMID 36899887, 2023). "During Leishmania infection, the participation of TLR-9, TLR-4, TLR-2, and TLR-3 is pivotal for mediating a proinflammatory cytokine response and subsequent infection control." (PMID 37111420, 2023). "Naringenin, a flavonoid product, is known to modulate mouse J774 macrophages upon infection with C. trachomatis, through modulation of TLR2, TLR4, and CD86 receptors and down-streaming of the MAPK (p38) pathway." (PMID 36982245, 2023). "The demonstration here that human, bacterial and fungal derived NDPKs converge on signaling via a common TLR4-independent NLRP3 inflammasome pathway, has implications for the role of infections in AML and MDS progression." (PMID 37418424, 2023).
infection (continued). "To explore the existence of TLR-TLR crosstalk, we therefore treated wildtype and Tlr4−/− iBMDMs with inhibitors of TLR2 (CU CPT22), TLR3 (TLR3/dsRNA complex inhibitor), and TLR9 prior to infection with C. neoformans." (PMID 37580395, 2023). "The present study reveals a shrimp LvCD14L-Tolls-NF-κB signaling pathway like the CD14/TLR4/NF-κB signaling pathway in mammalians, which enriches the functional mechanism of secretory LRR-only immune receptors during pathogens infection in invertebrates." (PMID 37175476, 2023). "Neutrophils or macrophages secret S100A8/A9 to magnify infection-induced inflammation by triggering advanced glycation end products (RAGE) and Toll-like receptor 4 (TLR4) signaling." (PMID 38093319, 2023). "The expression of several genes was downregulated following infection, including the chemokine receptor CXCR3 as well as pattern recognition receptors FPR2 and TLR4." (PMID 37138882, 2023). "Fc receptors (FcαR, FcyR), Toll-like receptor TLR2 and cell surface receptor and differentiation marker CD14 were exclusively overproduced in the presence of hSAA-1 and downregulated (FcyR, TLR2, TLR4, CD14) during infection." (PMID 37781389, 2023). "A study by Polari and coworkers described that in the context of human infection by L. braziliensis, the patient’s MΦ increased TLR2 and TLR4 and triggered TNF-α and IL-10." (PMID 37190011, 2023). "No increase was observed in the transcription of Toll-like receptors (TLR2, TLR4, TLR6) and TLR adaptor protein MYD88 during infection with any of the examined S. suis strains." (PMID 38276150, 2023). "Infection pathway-related molecules, for example IL-6, TNF, TLR4 and prostaglandins were commonly reported across these studies." (PMID 35379367, 2022). "Our results further showed that the recognition by the murine TLR4 was only partial, because of the escape of TLR4 internalization and subsequent TLR4-TRIF escape, potentially contributing to the chronicity of the infection in mice." (PMID 35937697, 2022). "This suggests that PT action inhibited the LOS/TLR4-elicted and ACT-potentiated chemotactic cDC outmigration from the site of infection." (PMID 35666769, 2022). "The TLR4/ERK1/2 MAPK/F-actin axis is necessary for Brucella internalization and has been exploited in many previous studies, even in the infection of other bacteria." (PMID 35631117, 2022). "HBeAg, not HBcAg, inhibited p38 phosphorylation in response to both LPS and Pam3Csy, suggesting that HBeAg is able to interfere with both TLR4 and TLR2 activation during infection." (PMID 36680092, 2022). "The results showed that after 24 hours of infection with UPEC CFT073, the expression of TLR4, TLR5 and myeloid differentiation Factor 88 (MyD88) mRNA in the 5637 (HTB-9) bladder epithelial cells increased significantly." (PMID 36506014, 2022). "By using a systemic model of TLR knock-out mice infection via the intraperitoneal route, TLR2 and TLR4 were shown to be dispensable for an efficient elimination of B. abortus." (PMID 35888979, 2022). "On mechanistic side, it is also possible that earlier in the infection, the amount of TMUV is too low to activate the TLR4 signaling pathway." (PMID 36379254, 2022). "However, in the context of infection, dampening TLR4 activation may be beneficial." (PMID 36246240, 2022). "Infection with M. gypseum induced a statistically significant upregulation of Dectin-1, TLR-2, and TLR-4 at 2, 5, and 14 dpi in the lung (p < 0.01); the peak of Dectin-1 emerged at 5 dpi, and TLR-2 and TLR-4 emerged at 2 dpi." (PMID 36233337, 2022). "Previously, we demonstrated that the TLR4 agonist monophosphoryl lipid A (MPLA) induces trained immunity and confers broad resistance to infection." (PMID 36439136, 2022).